NLRP3 (NLR family pyrin domain containing 3)
Diseases named in the same sentence as NLRP3 in open-access papers (continued):
Sharing a sentence is not in itself a finding about the gene and the disease.
colitis (continued). "Modulation of NLRP3 in the gut epithelium by high-fiber feeding has been suggested to contribute to intestinal homeostasis and protection from colitis through maintenance of a healthy microbiota and due to SCFA-mediated sensing by G-protein-coupled receptors GPR43 and GPR109A and IL-18 release." (PMID 26925061, 2016). "It has been reported that NLRP3 inflammasome is involved in DSS induced mice colitis." (PMID 27105524, 2016). "Furthermore, NLRP3 expression in mice with OXA-induced colitis reached a peak by day1 when severity of the colitis was at a maximum." (PMID 27966619, 2016). "We conclude that activation of CB2R ameliorates DSS-induced colitis through enhancing autophagy that may inhibit NLRP3 inflammasome activation in macrophages." (PMID 27611972, 2016). "NLRP6 and NLRP3 inflammasomes are both important for resisting DSS-induced colitis." (PMID 25879288, 2015). "This is in contrast to findings in experimental colitis in rodents, where NLRP3 is up-regulated." (PMID 25799280, 2015). "Upon chemical-induced colitis treatment, Nlrp3−/− mice lose epithelial cell integrity resulting in the dissemination of commensal bacteria, massive leukocyte infiltration, increased cytokine production, and ultimately higher mortality rates compared to wildtype mice." (PMID 25879288, 2015). "Defective NLRP3 inflammasome subtype activation was shown to protect against loss of epithelial integrity and mortality during DSS-induced experimental colitis, suggesting that genetic and environmental factors may activate the NLRP3 inflammasome." (PMID 26355424, 2015). "Moreover, it has been shown that Il18−/− or Il18r−/− mice are more susceptible to DSS-induced colitis and CRC, mimicking the increased tumor burdens observed in NLRP3 and caspase-1 deficient mice." (PMID 25071785, 2014). "Together, these studies indicate that NLRP3 plays a central role in regulating the integrity of the intestinal mucosal barrier under homeostatic conditions, and in shaping innate immune responses during experimental colitis." (PMID 25071778, 2014). "Interestingly, epithelial-derived IL-18 is also critical for protection against DSS colitis conferred by NLR-mediated signaling, as shown in studies using NLRP3 deficient mice." (PMID 25071778, 2014). "Equally, lack of epithelial IL-18 expression in NLRP3 deficient mice enhanced susceptibility of these mice to DSS-induced colitis when compared to control wild-type mice." (PMID 24886810, 2014). "Initially, NLRP3 was reported to have a key role in protecting intestinal homeostasis, as NLRP3-deficient mice were shown to have an altered microbiota and displayed increased susceptibility to DSS-colitis and tumorigenesis." (PMID 24381573, 2013). "Nlrp3, Asc and Caspase-1/11 KO mice are also hyper-sensitive to acute DSS colitis, with low colonic IL-18 levels associated with disease susceptibility, while administration of exogenous IL-18 ameliorates colitis severity." (PMID 23847622, 2013). "Infected Nlrp3−/− mice developed severe colitis; IL-1β treatments reduced colonization, abrogated dissemination of bacteria to mesenteric lymph nodes, and protected epithelial integrity of infected Nlrp3−/− mice." (PMID 24312491, 2013). "Furthermore, administration of exogenous IL-18 can alleviate the severity of colitis and colitis-induced tumorigenesis in caspase-1/11 and Nlrp3 KO mice." (PMID 23847622, 2013). "Previously, it was established that mice lacking the Nlrp3 gene were more susceptible to induced experimental colitis, and Nlrp3−/− macrophages did not respond to pathogen-associated microbial patterns." (PMID 24312491, 2013). "Furthermore, DCL exhibited protective effects in mouse models of NLRP3 inflammasome‐mediated diseases, including dextran sulfate sodium‐induced colitis, 2,4,6‐trinitrobenzenesulfonic acid‐induced Crohn's disease, LPS‐induced septic shock, and monosodium urate‐induced peritonitis." (PMID 40919130, 2025).
colitis (continued). "Therefore, we hypothesize that NF-κB potentiation by Ile may subsequently prime and potentially enhance the activation of the NLRP3 inflammasome, forming a pro-inflammatory positive feedback loop that aggravates colitis." (PMID 41394102, 2025). "Differential expression of NLRP3 may lead to varied outcomes, potentially due to variations in the genetic backgrounds of mice and humans, differences in gut microbiota composition, the selected colitis model, or the colitis induction method." (PMID 40433382, 2025). "Furthermore, NLRP3 has a beneficial role in probiotic-centered treatment for colitis." (PMID 41149694, 2025). "Employing a DSS-induced colitis framework, our research focused on assessing the influence of A. cristatum on factors such as inflammatory cytokines, intestinal barrier integrity, expression of tight junctions, and the dynamics within the NLRP3 signaling pathway." (PMID 40001993, 2025). "Similarly, geniposide was found to inhibit NLRP3 inflammasome activation via autophagy in BV-2 microglial cells exposed to oxygen–glucose deprivation/reoxygenation, and to ameliorate dextran sulfate-induced colitis in mice via the Nrf2/HO-1/NF-κB pathway." (PMID 40142139, 2025). "NLRP3 inflammasome activation in the gut causes excessive inflammation during IBD; however, defective NLRP3 inflammasome formation results in a loss of gut epithelial integrity, bacterial overgrowth, and increased susceptibility to dextran sodium sulfate (DSS)-induced colitis." (PMID 41062723, 2025). "By using a TLR4 overexpression plasmid, we found that ruscogenin treatment potentially alleviates DSS-induced colitis in mice by inhibiting NLRP3 inflammasome activation and canonical pyroptosis, and the protective effect may be related to the suppression of the TLR4/NF-κB signaling pathway." (PMID 38790951, 2024). "Therefore, the suppression of the NF-κB and NLRP3 pathway may be an effective target to reduce colitis." (PMID 38674869, 2024). "Our previous research found that the cholesterol metabolism intermediate dehydroepiandrosterone (DHEA) can negatively regulate NLRP3 inflammasome activation and alleviate intestinal inflammation in colitis mice, and may serve as a nutritional supplement for preventing IBD." (PMID 39334766, 2024). "Additionally, DSS-induced colitis mice show enhanced IL-1β level produced by NLRP3 inflammasome." (PMID 38417794, 2024). "Additionally, it reverses the activation of NLRP3 in colonic macrophages of colitis-afflicted mice." (PMID 39668979, 2024). "Similarly, flow cytometry analysis revealed the percentage of CD11b + CD11c+ M1-macrophage was not decreased by CGA in colonic tissue of Nlrp3-deficient mice during colitis." (PMID 37813835, 2023). "Hence, we next sought to determine whether Nlrp3 can be targeted to treat the severe colitis by regulating macrophage polarization." (PMID 37813835, 2023). "Our results find that Ononin may alleviate colitis by inhibiting macrophage NLRP3 inflammasome." (PMID 36840499, 2023). "Moreover, studies conducted on mice with NLRP3 knockout have shown their resistance to colitis." (PMID 37841914, 2023). "Interestingly, when colitis was induced in NLRP3-deficient mice, inflammatory pathology was absent in both the gut and brain, clearly identifying a central role for this structure and the inflammation it triggers." (PMID 36769140, 2023). "Thus, the NLRP3 inflammasome plays a crucial part in the pathogenesis of colitis, and the control of NLRP3 inflammasome activation could improve the symptoms of UC." (PMID 36762118, 2023). "In addition, inhibitors of the NLRP3 inflammasome significantly alleviated colitis symptoms." (PMID 36840499, 2023). "Enhanced inflammasome activity manifested in mice prior to onset of colitis and the disease could be successfully treated by blockade of NLRP3 inflammasomes or IL-1β signaling demonstrating that symptoms of IL-10 deficiency are mediated by inflammasome perturbation." (PMID 36524121, 2022).
colitis (continued). "Notably, a detrimental role of NLRP3 in DSS colitis has also been reported, indicating that the contribution of NLRP3 to DSS-induced colitis may be different between the induction- and recovery phase of this model." (PMID 35693797, 2022). "Thus, targeting IL-17 signaling may also affect the activation of NLRP3 inflammasome and contribute to progression of colitis." (PMID 36090968, 2022). "Dextran sulfate sodium (DSS)-induced colitis caused amyloid plaque accumulation, compromised glymphatic clearance and increased infiltration of gut-derived T-cells, and triggered cortical and hippocampal degeneration mediated by NACHT-LRR and PYD-containing protein 3 (NLRP3) inflammasome expression." (PMID 35281490, 2022). "Moreover, NR1D1, as a transcriptional repressor, could repress the NF-κB/Nlrp3 axis to prevent colitis." (PMID 35893911, 2022). "Moreover, selective blockade of the NLRP3 inflammasome could ameliorate colonic inflammation in a colitis model." (PMID 35330829, 2022). "Therefore, the possible anti-inflammatory action of Se on colitis may be related to the inhibition of NF-κB and NLRP3 pathways." (PMID 35745163, 2022). "Therefore, to further explore whether the alleviative effect of OCOP and COP was associated with inhibition of NLRP3 inflammasome and NF-κB pathway in DSS-induced colitis, relevant signal molecules were examined." (PMID 33859564, 2021). "Thus, CAI might exert its anti-colitis role by inhibiting the NLRP3 inflammasome and NF-kB signaling." (PMID 33808793, 2021). "However, the mechanism through which CaSR activates NLRP3 in colitis needs further study." (PMID 34880751, 2021). "Therefore, the effect of RA in ameliorating colitis might be exerted through its inhibition of the expression of NLRP3 inflammasome components." (PMID 33808793, 2021). "Among genes encoding inflammasome components, IL1B and NLRP3 are highly expressed in colon cancer tissues 40,41, and accumulating evidence points to critical roles of the inflammasomes and IL-1β in dextran sulfate sodium (DSS)-induced colitis and azoxymethane (AOM) plus DSS-induced CAC." (PMID 33686176, 2021). "A study with dextran sulphate sodium (DSS)-induced murine colitis by targeting the inflammasome NLRP3, demonstrated that genistein inhibited NLRP3 inflammasome through macrophage TGR5-cAMP signaling, demonstrating that this could be a potentially effective drug for IBDs." (PMID 33499333, 2021). "Thus, hypoxia might regulate the development of colitis by downregulating the NLRP3/mTOR pathway and activating autophagy in the colon of Crohn’s disease patients and mice with colitis." (PMID 33808793, 2021). "Thus, NLRP3 inflammasome is one of the targets of naringin in preventing DSS-induced colitis." (PMID 33808793, 2021). "Herein, we found that lactic acid-producing S. cerevisiae not only suppressed M1 macrophage polarization but also inhibited the NLRP3 inflammasome in vivo and in vitro, indicating that lactic acid-producing S. cerevisiae may exert this synergistic effect for protection from colitis." (PMID 34899735, 2021). "Yet, experimental colitis in mice deficient in NLRP3 could not prove an unequivocal pro-inflammatory role of NLRP3." (PMID 34344313, 2021). "In addition, H2S attenuated the severity of mouse colitis by NLRP3 inflammasome inhibition." (PMID 33682108, 2021). "It provides that AMPK could be a target to control NLRP3 inflammasome activation and colitis." (PMID 32950971, 2020). "However, other studies have shown that mice lacking NLRP3 are more susceptible to colitis-related colorectal cancer, indicating that the NLRP3 inflammasome has an antitumor role in colitis-associated cancer." (PMID 32303673, 2020). "H2S could reduce the inflammation of colitis induced by DSS through inhibiting the activation of NF- κB pathway, so it could be infered that H2S could relieve DDS-induced colitis through suppressing NLRP3 inflammasome via NF- κB pathway, which neede further study 92-95." (PMID 33110394, 2020).
colitis (continued). "Recently, it was shown that the NLRP3 inflammasome, which is a complex that contains NLRP3, ASC, and caspase-1, plays an important role in colitis and colitis-associated colon cancer (CAC) and is also known as a potential target for the prevention of colitis and CAC." (PMID 33312339, 2020). "This hypothesis was proven true by administering mice MCC950, a specific inhibitor of the NLRP3 inflammasome, as MCC950 administration reduced the severity of colitis in Slco2a1-deficient mice via suppressing the expression of mature IL-1β and cleaved caspase-1." (PMID 32184453, 2020). "However, both RSV and C33 suppressed the NLRP3 expression induced by colitis." (PMID 31885813, 2019). "Therefore, we assessed whether E. faecalis pretreatment can protect mice from acute colitis by reducing NLRP3 inflammasome activation, as assessed by monitoring weight loss and diarrhea in the DSS-treated mouse model." (PMID 30823406, 2019). "Several articles have demonstrated that administration of CAI, oroxylin A, or wogonoside could alleviate the severity of experimental colitis, suppress the mucosal inflammation, which might be attributed to its inhibition of NF-κB and NLRP3 inflammasome activation." (PMID 30873162, 2019). "Indeed, hyper-activation of the NLRP3 inflammasome can lead to colitis in different contexts." (PMID 31091682, 2019). "However, the role of NLRP3 inflammasome in colitis is controversial." (PMID 31091682, 2019). "This hypothesis may explain the protective effect of NLRP3 inhibition on DSS-induced colitis." (PMID 30588399, 2018). "In view of these findings one might ask why IL-10-deficient mice with secondary increases in NLRP3 deficiency not develop increased regulatory cell activity that prevents colitis." (PMID 30455704, 2018). "Furthermore, miR-223 in the inflammatory mononuclear cells could directly mediate NLRP3, in order to moderate the activity of the inflammatory corpuscle and inhibit colitis." (PMID 29416535, 2018). "More importantly, the inhibition of NLRP3 pathway could mitigate the disease severity of colitis." (PMID 29507526, 2018). "Therefore, we assessed whether decreasing negative regulation of the NLRP3 inflammasome activation could attenuate colitis in an animal model by treating DSS-exposed mice with the Cbl inhibitor, hydrocotarnine." (PMID 30382081, 2018). "Consequently, we further investigated whether TER could inhibit NLRP3 inflammasome activation in DSS-induced colitis mice." (PMID 28553294, 2017). "Therefore, the possible effects of the pharmacological blockade of IL-1β receptor in different animal models of colitis should be investigated, in order to find out the better strategy to inhibit the NLRP3 inflammasome pathway and counteract bowel inflammation." (PMID 28179906, 2017). "In addition, HE staining and histological analysis revealed a remarkable improvement of pathological changes in NLRP3-/- mice compared with the WT during colitis progression, including reduction of necrosis, mucosal damage and less distribution of inflammatory cells." (PMID 28938606, 2017). "It has been documented that NLRP3 inflammasome may play crucial roles in DSS-induced colitis." (PMID 27105502, 2016). "In addition, NLRP3−/− mice revealed severe colitis with increased expression of Th2 cytokines." (PMID 27966619, 2016). "In conclusion, these results suggest that the NLRP3 inflammasome may have a protective effect on Th2 cytokines- and immune system-mediated experimental colitis; both the inflammasome derived IL-1β and IL-18 contribute to this protection via different mechanisms." (PMID 27966619, 2016). "We showed that exogenous IL-1β, as well as exogenous IL-18, improved OXA-induced colitis in WT mice and prevented worsening of colitis in NLRP3−/− mice, strongly suggesting that the NLRP3 inflammasome-derived IL-1β may have an inhibitory effect on OXA-induced colitis." (PMID 27966619, 2016). "However, other studies showed that colitis in rodents is actually mediated by NLRP3." (PMID 25799280, 2015).
colitis (continued). "rhMG53 administration ameliorated colitis severity in MG53 -/- mice and dose-dependently suppressed NLRP3 inflammasome activation in vitro." (PMID 41929244, 2026). "Taken together, these results indicated that O. splanchnicus promotes the transformation of LCA to modulate NET formation and degradation via the NLRP3‐GSDMD pathway, contributing to a protective effect in colitis mice." (PMID 40990446, 2025). "Myeloid knockout of Vangl2 enhances the activation of NLRP3 inflammasome and exacerbates the progression of DSS-induced colitis in mice." (PMID 39899477, 2025). "This compound also modulated the NLRP3-Cas-1-GSDMD-IL-1β inflammatory pathway and inhibited the NF-κB (nuclear factor kappa B) pathway, thereby alleviating colitis." (PMID 40238502, 2025). "Generally, activation of the NLRP3 inflammasome in IBD can exacerbate inflammation, worsen colonic injury, or ameliorate colitis to prevent further damage." (PMID 40433382, 2025). "Studies have demonstrated that mice with NLRP3 knockout, when exposed to DSS, exhibit lower levels of proinflammatory cytokines in colonic tissue and manifest less severe colitis compared to their WT counterparts." (PMID 39934686, 2025). "Our current findings demonstrate that A. cristatum treatment substantially diminishes the expression of key NLRP3 inflammasome components including NLRP3, ASC, and Caspase-1 in a model of DSS-induced colitis." (PMID 40001993, 2025). "The tetracyclic triterpene derivative ginsenoside Rd mediates NLRP3 inflammasome inactivation via induction of P62-driven mitochondrial autophagy, which significantly attenuates the severity of DSS-induced colitis in UC mice." (PMID 40842999, 2025). "Animal experiments have shown that NLRP3−/−, ASC−/−, and caspase-1−/− mice exhibit significant protective effects in the DSS-induced colitis model." (PMID 40871494, 2025). "Dysregulated NLRP3 inflammasome contributes to the pathogenesis of colitis, we then employed a dextran sulfate sodium (DSS)‐induced acute colitis model." (PMID 40948397, 2025). "For instance, the experimental colitis induced by DSS or 2,4,6-trinitrobenzenesulfonic acid was significantly alleviated by either knocking out NLRP3 and caspase-1 genes or administering pyroptosis inhibitors." (PMID 40041420, 2025). "Using LPS/ATP-induced RAW264.7 cells and DSS-induced colitis in mice, CGA was shown to reduce NLRP3 inflammasome-related proteins and miR-155 expression, suggesting a potential therapeutic strategy for UC." (PMID 40225345, 2025). "Andrographolide, a herbal extract, enhances mitochondrial autophagy in macrophages, inhibits the NLRP3 inflammasome, and ameliorates DSS-induced colitis." (PMID 40433382, 2025). "Taken together, we identified VANGL2 as a negative regulator of NLRP3 inflammasome and involved in regulating the pathogenesis of DSS-induced colitis." (PMID 39899477, 2025). "Colitis induction significantly elevated macroscopic damage scores, stool consistency, inflammatory cytokines, MDA, MPO, and NLRP3, NF-κB, caspase-1, while reducing GSH levels (p < 0.001-0.01)." (PMID 40320895, 2025). "The authors also showed that the polysaccharide-modulated key signaling pathways, including the NF-κB, MAPK, and PPARγ signaling pathways, inhibited the NLRP3 inflammasome signaling pathway, resulting in a reduction in DSS-induced colitis inflammation." (PMID 40283898, 2025). "Our study showed that the NLRP3 inflammasome is activated in both IBD patients and DSS-induced colitis in mice." (PMID 39899477, 2025). "In colitis, the NLR family pyrin domain containing 3 (NLRP3) inflammasome is activated and assembled, contributing to maturation processes." (PMID 39966502, 2025). "In animal models, wedelolactone alleviated DSS-induced colitis by blocking NF-κB and MAPK pathways, suppressing NLRP3 inflammasome activation, and promoting AMPK signaling, thereby reducing IL-1β release and tissue injury." (PMID 41304898, 2025).